IL34 (interleukin 34)
Diseases named in the same sentence as IL34 in open-access papers (continued):
Sharing a sentence is not in itself a finding about the gene and the disease.
autoimmune disease (12 papers, 2017 to 2025). A disorder resulting from loss of function or tissue destruction of an organ or multiple organs, arising from humoral or cellular immune responses of the individual to their own tissue constituents. "A newly discovered cytokine interleukin-34 (IL-34) is closely associated with various inflammatory and autoimmune diseases." (PMID 30478377, 2018). "The findings that IL-34 could promote the production of some chemokines associated with inflammation and autoimmune diseases indicated that IL-34 might play multiple roles in the pathology of RA." (PMID 28659662, 2017). "Interleukin 34 (IL-34) is a molecule whose expression is increased in conditions such as autoimmune disorders, inflammation, and infections." (PMID 38626032, 2024). "In human, the administration of IL‐34 represents a new therapeutic strategy for the treatment of autoimmune diseases, GVHD and transplant rejection." (PMID 36030499, 2022). "More and more evidences show that IL-34 is involved in the etiology of various diseases, such as inflammation, infection, autoimmune diseases, and tumors." (PMID 34095310, 2021). "Infliximab, a chimeric monoclonal antibody and a medication used, among others, to treat a number of autoimmune diseases, reduces the expression of the interleukin-34 (IL-34) involved in monocyte and macrophage differentiation, survival, and function." (PMID 33456458, 2020). "IL-34 was first described in 2008, and its involvement in the development of many autoimmune diseases has been recently identified." (PMID 30405534, 2018). "Indeed, several studies have confirmed that IL-34 expression is increased at mRNA and protein levels in the context of various diseases, including autoimmune disorders, inflammation, and infections." (PMID 38626032, 2024). "Furthermore, intra-hepatic IL-34 expression was consistent with circulating IL-34, which is in line with previous studies, showing that high IL-34 in autoimmune diseases." (PMID 35347503, 2023). "IL-34 is suspected of playing a role in various other autoimmune diseases." (PMID 33408768, 2021). "However, the majority of studies have shown that IL-34 could be a pro-inflammatory factor in kidney injury, autoimmune diseases, cancers, infectious disease and MI/R." (PMID 39883639, 2025). "IL‐34 upregulation has been associated with certain but not all autoimmune diseases." (PMID 36030499, 2022). "Recently, Iranian scientists have found that serum IL-34 levels in patients with acute and chronic inflammatory demyelinating polyneuropathies (AIDP and CIDP) are elevated, suggesting that IL-34 may participate in the pathogenesis of autoimmune diseases." (PMID 34095310, 2021).
ovarian carcinoma (12 papers, 2015 to 2025). A malignant neoplasm originating from the surface ovarian epithelium. "Studies in ovarian cancer confirmed the induction of IL-34 in cancer cells by cytotoxic chemotherapy and the reduced overall survival of patients with high IL-34 expression." (PMID 36765929, 2023). "Many other studies documented the contribution of IL-34 in other malignancies, such as haematological tumours, brain, breast, neck, biliary, and ovarian cancers." (PMID 34535634, 2021). "IL-34 promotes differentiation of monocytes into IL-10-expressing, immunoregulatory macrophages, which exhibit similarities to TAMs seen in ovarian cancer." (PMID 34535634, 2021). "IL-34 levels increase in ovarian cancer cell lines following treatment with cytotoxic agents and in the tumor tissues of chemotherapy-given ovarian cancer patients." (PMID 31968663, 2020). "IL-34 producing ovarian cancer cell line HM-1 was treated by bromodomain and extra terminal inhibitor JQ1." (PMID 33072227, 2020). "There is another clinical fact that IL-34 expression in cancer correlates with poor prognosis and higher disease stage in several types of cancers such as brain, lung, ovarian cancers, and melanoma." (PMID 33072227, 2020). "Moreover, IL-34 exerted a profound influence on TAMs via CSF-1R signaling in ovarian cancer as in fact IL-34 facilitated the differentiation of monocytes into TAMs expressing membrane IL-1α (mIL-1α) and IL-18." (PMID 39457693, 2024). "Notably, high IL-34 expression correlates with worse progression-free survival and overall survival in different cohorts and in a mouse model of ovarian cancer." (PMID 31968663, 2020). "IL-34 is also expressed in human ovarian cancer cell lines and tissues." (PMID 31968663, 2020). "The contribution of IL-34 in cancer is also supported by many other studies, documenting an enhanced expression of the cytokine in various neoplastic diseases, including hematological malignancies, brain, breast, neck, biliary, and ovarian cancer." (PMID 31968663, 2020). "BRD4 is also a critical regulator of cancer cell growth and survival, and studies in ovarian cancer cells have recently shown that BRD4 binds the promotor region of the IL-34 gene and regulates IL-34 production." (PMID 39451216, 2024). "Our data confirm and expand on results from previous studies showing that JQ1 inhibits IL-34 expression in the murine ovarian cancer cell lines OV3121-RAS4 and HM-1, and this effect was not due to changes in cell viability." (PMID 39451216, 2024). "Additionally, IL-34- and MCSF-induced macrophages can switch memory T cells into Th17 cells to support anti-tumour immunity in established ovarian cancers." (PMID 32765828, 2020). "Moreover, in a mouse model of ovarian cancer, lack of IL-34 attenuated tumor progression, and this finding was associated with reduced increased infiltration of the tumors with T lymphocytes." (PMID 36765929, 2023).
Alzheimer disease (10 papers, 2014 to 2025). A progressive, neurodegenerative disease characterized by loss of function and death of nerve cells in several areas of the brain leading to loss of cognitive function such as memory and language. "Interestingly, a relatively common stop-gain mutation in human IL34 (Y213Ter, minor allele frequency ca. 0.1) has been associated with an increased relative risk of developing Alzheimer’s disease." (PMID 40533345, 2025). "Intriguingly, a stop-gain mutation in the IL34 gene may confer risk for Alzheimer’s disease (AD) in humans." (PMID 38766127, 2025). "The presentation concluded with new data showing that HIV-1 neuropathogenesis can be studied alongside Alzheimer’s disease in immunodeficient mice that combine transgenic expression of human IL-34 with modifications to the mouse amyloid precursor protein gene." (PMID 41221300, 2025). "Further, IL34 expression levels are decreased (while CSF1 levels are increased) in Alzheimer’s disease and in animal models, and IL34 infusion is sufficient to rescue associative learning deficits in APP/PS1 mice." (PMID 38766127, 2025). "In neurodegenerative diseases, IL-34 primarily produced by neurons promoted microglia differentiation and proliferation via the CSF-1R receptor in an Alzheimer disease (AD) mouse model." (PMID 33408768, 2021). "To approach this question, we also sought to identify differences between IL-34, CSF-1, and CSF-1R expression in human brain samples to establish whether there was an imbalance in Alzheimer's disease (AD)." (PMID 28848420, 2017). "The novel function of IL-34 on the blood–brain barrier may give us a clue for new therapeutic strategies in neuroinflammatory and neurodegenerative diseases such as multiple sclerosis and Alzheimer's disease." (PMID 25535736, 2014).
colon cancer (10 papers, 2018 to 2025). "For example, in lung and colon cancers, IL34 sustains tumor growth by promoting cancer cell proliferation and survival through CSF1R activation, whereas in glioblastoma cells, IL34 inhibits tumor proliferation through PTP-ζ activation." (PMID 40538439, 2025). "A previous study has demonstrated the critical role of IL-34 in colon cancer cell proliferation and tumorigenesis." (PMID 33800170, 2021). "This is the first study showing that, in colon cancer, IL-34 is produced by CAFs and targets these cell populations with the down-stream effect of enhancing the CAF pro-tumorigenic function." (PMID 33260828, 2020). "Interleukin-34 (IL-34) is a cytokine overproduced by colon cancer (CRC) cells and supposed to make a valid contribution to the growth and diffusion of CRC cells." (PMID 33298879, 2020). "IL-34 mediates resistance to oxaliplatin in colon cancer cells in an ERK1/2-dependent manner, as suggested by the cell chemosensitization induced by the pharmacological inhibitors of ERKs." (PMID 31117237, 2019). "Moreover, ERKs mediate proliferation and/or migration in response to IL-8 in pancreatic and cervical cancer, to IL-34 in colon cancer cells, and to IL-13 in glioblastoma multiforme, working as downstream collectors of the pro-tumorigenic inputs of different cytokines." (PMID 31117237, 2019).
colorectal cancer (10 papers, 2015 to 2023). A primary or metastatic malignant neoplasm that affects the colon or rectum. "As for blood cancer cases and colorectal cancer, we found that a lower expression of the IL-34 gene was associated with poor survival." (PMID 25395235, 2015). "IL‐34 is expressed on several solid cancers including colorectal cancer and hematological malignancies." (PMID 35132816, 2022). "In colorectal cancer, high levels of IL-34 correlated with TAM infiltration and a poor prognosis for the affected patients." (PMID 33408768, 2021). "A recent study demonstrated that IL-34 was expressed in colorectal carcinoma patient samples and induced the proliferation and invasion of colorectal cancer cells." (PMID 33408768, 2021). "Cytokines also play important role in COAD, for example, interleukin-34 (IL-34) expression is upregulated in colorectal cancer and promotes cancer cell growth; interleukin-23 (IL-23)-induced immune cell activation exacerbates intestinal inflammation and promotes COAD growth." (PMID 34900677, 2021). "various types of cancers over-express IL-34 but the role of the cytokine in colorectal cancer (CRC) remains unknown." (PMID 29423057, 2018). "In colorectal cancer, IL34 has been shown to regulate the modulators Netrin-1 and b-FGF in colorectal CAFs, thereby influencing the behavior of colorectal cancer cells." (PMID 38081923, 2023).
glioblastoma (10 papers, 2015 to 2025). The most malignant astrocytic tumor (WHO grade IV). "Noteworthy, IL-34 selectively bound PTPRZ1 in CSF-1R-deficient U251 human glioblastoma cells and led to an increase in the tyrosine phosphorylation of FAK and suppression of cell motility." (PMID 29796177, 2018). "For example, IL-34 hinders the proliferation, clonogenicity, and motility of glioblastoma cells and promotes the differentiation of monoblastic leukemia cells into monocyte-like cells." (PMID 35936748, 2022). "The interaction between IL-34 and RPTP-ζ induced tyrosine phosphorylations of the FAK and paxilin proteins, impairing the cell proliferation and motility of U251 glioblastoma cells." (PMID 33408768, 2021). "IL34, however, is downregulated in glioblastoma and thus does not play a significant role in CSF-1R signalling in glioblastoma." (PMID 33803414, 2021). "IL-34 binds to the extracellular domain of PTPRZ1 to stimulate the phosphorylation of paxillin and focal adhesion kinase, which influences the growth and migration of glioblastoma cells." (PMID 31727934, 2019). "An additional receptor of IL-34, receptor-type protein-tyrosine phosphatase ζ (PTPRZ1, RPTP-ζ), was recently identified by Nandi and colleagues who showed signalling through PTPRZ1 by IL-34, but not CSF-1, in mouse brain and in the human glioblastoma cell line U251." (PMID 27898738, 2016).
heart failure (10 papers, 2016 to 2026). Inability of the heart to pump blood at an adequate rate to meet tissue metabolic requirements. "Interestingly, the scientific research team of Shanghai Jiao tong University found that increased levels of IL-34 in the acute phase are associated with increased risk of heart failure and poor prognosis after myocardial infarction." (PMID 34095310, 2021). "Also new tools such as global longitudinal strain are needed to evaluate cardiac function more accurately, further confirming the association between IL-34 and heart failure." (PMID 30050466, 2018). "However, the direct impact of IL-34 on heart failure and the underlying mechanisms needs to be further studied." (PMID 27982136, 2016). "Serum IL-34 was also found to be associated with heart failure in our previous study." (PMID 27982136, 2016). "Increased IL-34 levels have been significantly linked to ischemic cardiomyopathy and may serve as an indicator for cardiovascular death, decompensation-related hospitalization, and all-cause mortality in heart failure patients." (PMID 38166811, 2024). "Previous studies have demonstrated that elevated levels of IL-34 correlate with poor outcomes in patients with heart failure, particularly those with chronic renal failure or insufficiency." (PMID 40176879, 2025). "Elevated IL-34 levels also correlate with heightened heart failure presence and severity in acute myocardial infarction patients, along with increased cardiovascular mortality." (PMID 38166811, 2024). "However, it is unclear whether IL-34 plays a maladaptive or a compensatory role in the pathogenesis of renal impairment, or only reflects the underlying renal dysfunction in patients with heart failure." (PMID 27982136, 2016). "Renal destruction secondary to low renal blood flow is similar to that with ischemic injury, which in part explains the reason why serum IL-34 is up-regulated in heart failure-induced kidney dysfunction." (PMID 27982136, 2016). "The role of IL-34 in assessing the prognosis of heart failure needs to be assessed in future cohort studies." (PMID 27982136, 2016). "On the basis of several experimental studies, it is reasonable to conclude that IL-34 has a participatory role in the pathophysiology of renal impairment, in addition to reflecting the severity of heart failure." (PMID 27982136, 2016). "In the present study, serum levels of IL-34 were found to be independently associated with renal biomarkers including eGFR and cystatin C among patients with HF, suggesting that IL-34 may play an important role in the process of heart failure mainly owing to its effect on renal function." (PMID 27982136, 2016). "Notably, dysregulated inflammatory responses have become a focus of therapeutic intervention, with IL-34-centered immunomodulation showing promise in preventing heart failure after AMI." (PMID 41538664, 2026). "In addition, a substantial circulating IL-34 level has been detected in CAD patients and is associated with the severity of comorbid CAD in heart failure." (PMID 34422917, 2021). "However, little is known about the role and clinical significance of IL-34 in renal function and coronary artery lesions during heart failure." (PMID 27982136, 2016). "Moreover, studies have shown that IL-34 may be an important predictor of CVD, heart failure hospitalization, and all-cause mortality in patients with chronic heart failure (CHF)." (PMID 36698935, 2022). "Moreover, serum IL-34 level was significantly positively correlated to NT-proBNP level (r = 0.223, P < 0.001), left ventricular end diastolic diameter and New York Heart Association (NYHA) functional class, indicating that a higher IL-34 level reflects more severe heart failure (HF)." (PMID 30050466, 2018). "Thus, IL-34 may have a role to play in the pathogenesis of heart failure mediated by galectin-3." (PMID 27982136, 2016). "Similarly, IL-34 has been established as a prognostic biomarker in both CAD and heart failure, alike." (PMID 36769623, 2023).
heart failure (continued). "So that the relationship between serum IL-34 level and the risk of cardiac dysfunction, especially in patients with CAD but without heart failure at baseline, needs to be illustrated in larger cohorts to prospectively confirm the predictive value of it." (PMID 30050466, 2018).
viral infection (10 papers, 2017 to 2025). "–66 Our study revealed an upregulation of ribosomal and other host genes including RNA polymerases and IL34 which are associated with viral infection, supporting that viruses may be integral to the pathophysiology of PEX." (PMID 35348588, 2022). "In both cases, IL-34 could be considered as an interesting candidate for generation of antiviral treatments or as a target to reduce its pathogenic contribution during viral infection." (PMID 33408768, 2021). "In addition, West Nile virus infection can cause cognitive impairment, and IL-34 knockout mice can reduce the synaptic loss caused by this virus infection, suggesting that IL-34 may participate in the course of cognitive impairment." (PMID 34095310, 2021). "There are a limited number of studies evaluating the relationship between IL-34 and viral infections." (PMID 38626032, 2024). "Theranostic applications include specific delivery of recombinant IL-34 in patients affected by diseases where IL-34 has been described as a protective or beneneficial molecule, e.g. CNS diseases, viral infections or liver transplantations." (PMID 33408768, 2021). "Overall, these data suggest that IL-34 induces differential transcription programs and functions compared to CSF-1 during viral infection in high vertebrates and that IL-34 is able to display antagonist roles during viral infection." (PMID 33408768, 2021). "Secondly, hyper activation of pro-inflammatory by IL-34 in response to viral infection promotes viral expansion and tissue damage as has been observed in HCV, HBV, and HFRS affected patients." (PMID 33408768, 2021). "It has been indicated that IL-34 can be induced by various stimuli such as chemotherapy, chemical stressors, pro-inflammatory cytokines, PAMPs, vitamin D, and viral infections in a wide range of cells via an NF-κB-mediated mechanism." (PMID 33072227, 2020). "IL-34 expression can be induced by various stimuli such as DNA-damaging agents, chemical stressors, pro-inflammatory cytokines, viral infection, and vitamin D. In humans, IL-34 is found in a variety of tissues, including heart, brain, lung, liver, kidney, prostate, and colon." (PMID 38626032, 2024). "The upregulated genes associated strongly with microglial activation and included antigen presentation genes (Tap1, B2m) and activation genes (Ccl12, IL-34 and Icam1) that occur in neurodegenerative disease, brain injury and viral infection, and are NF-κB regulated." (PMID 35464428, 2022). "IL-34 plays an important role during viral infections in other species." (PMID 33408768, 2021). "In terms of virus infection, IL-34 could response to influenza A virus (IAV) infection through the inflammatory cascade." (PMID 28614380, 2017). "However, IL34 is known to be upregulated in response to viral infection." (PMID 35348588, 2022). "IL-34 can firstly induce antiviral response by activation of a specific set of genes that block viral replication, as has been observed in HIV-1 and FV3 viral infection." (PMID 33408768, 2021).
Sjogren syndrome (9 papers, 2015 to 2024). An autoimmune disorder in which immune cells attack and destroy the glands that produce tears and saliva. "This is intriguing as IL-34 has been associated with local inflammation in other chronic inflammatory diseases including RA and Sjögren's syndrome." (PMID 25896238, 2015). "There is an increasing interest in IL-34 and CSF-1, where IL-34 overexpression was observed in inflammatory conditions including Sjögren’s syndrome, whereas overexpression of IL-34 and CSF-1 was reported for RA and IBD." (PMID 27898738, 2016). "The increase in IL-34 correlated with the expansion of pro-inflammatory monocytes and expression of IL-23 and IL-17, suggesting that IL-34 plays an important role in the inflammatory process in Sjogren's syndrome." (PMID 33408768, 2021). "Furthermore, IL-34 expression is up-regulated in inflamed salivary glands from patients with Sjögren's syndrome." (PMID 25896238, 2015).